RN7SL677P (RNA, 7SL, cytoplasmic 677, pseudogene)
Gene: Miscellaneous RNA gene on chromosome 15 (97,353,497 to 97,353,815, forward strand). Ensembl gene ENSG00000242863.
Homologues: Orthologues: chimpanzee Metazoa_SRP (96% identical). Paralogues in human: RN7SL3 (72% identical), RN7SL2 (71% identical), RN7SL1 (71% identical), RN7SL559P (71% identical), RN7SL220P (70% identical), RN7SL126P (70% identical), RN7SL5P (70% identical), RN7SL397P (69% identical), RN7SL566P (69% identical), RN7SL464P (69% identical), RN7SL28P (68% identical), RN7SL45P (68% identical), and 697 more.